YAP1 (Yes1 associated transcriptional regulator)
Diseases named in the same sentence as YAP1 in open-access papers (continued):
Sharing a sentence is not in itself a finding about the gene and the disease.
lymph node metastasis (22 papers, 2013 to 2025). "Among clinically recognized features such as lymph-node metastasis and T stages, YAP1 activation was significantly associated with HPV status (P = 4.29 × 10-7)." (PMID 29340043, 2017). "A recent study showed that YAP1 overexpression was associated with the progression, lymph node metastasis, and poor prognosis of GC." (PMID 27835600, 2016). "The results indicated that high PP1γ expression was significantly associated with lymph node metastasis (P = 0.004), while high YAP1 expression was significantly related to male gender (P = 0.042), lymph node metastasis (P < 0.01), and advanced AJCC stage (P = 0.012)." (PMID 40626009, 2025). "The ectopic expression of YAP1 is associated with lymph node metastasis." (PMID 38136338, 2023). "High YAP1 levels are positively associated with lymph node metastasis and poor prognosis of GC." (PMID 31689236, 2019). "As an important component of the TEAD-1-YAP complex, YAP1 upregulation in cytoplasm is associated with histologic grading, lymph node metastasis, and recurrence of cervical SCC, and its nuclear overexpression is associated with shorter OS and disease-free survival of cervical adenocarcinoma." (PMID 30344797, 2018). "Consistently, the results of this study showed that the high expression of YAP1 was associated with male gender, late AJCC stage, and lymph node metastasis." (PMID 40626009, 2025). "YAP1 and TAZ expressions are associated with lymphatic metastasis of human ESCC, and YAP is selectively activated in lymph node metastatic tumors, upregulating genes for fatty acid oxidation." (PMID 40507333, 2025). "Stromal nuclear YAP1 positivity was associated with adverse clinicopathologic features, including higher Gleason score, elevated PSA, advanced T stage, and lymph node metastasis or seminal vesicle invasion." (PMID 41514658, 2025). "With lymph node metastasis (OR 0.270, 95% CI 0.091–0.801, p = 0.018), high YAP1 expression remained an independently significant parameter with ODX low risk, RS ≤26 (OR 0.373, 95% CI 0.198–0.703, p = 0.002)." (PMID 37894401, 2023). "ER negativity, PR negativity, tumor size >2 cm, lymph node metastasis, and high nuclear YAP1 expression were significant factors in the multivariate analysis of DFS." (PMID 33718163, 2021). "Lymph node metastasis and high nuclear YAP1 expression were significant determinants of poor DMFS in the univariate analysis." (PMID 33718163, 2021). "Recent study found that YAP1 activation resulted in fatty acid oxidation and developed lymph node metastasis in mouse model." (PMID 33970925, 2021). "In multivariate Cox analysis, the age, lymph node metastasis status and up-regulated YAP1 expression are independent prognostic factors of poor prognosis." (PMID 33123286, 2020). "Multivariate regression analysis showed that age, lymph node metastasis status and the mRNA level of YAP1 were independent prognostic factors." (PMID 33123286, 2020). "The previous study also reported a statistically significant relation between YAP1 expression and larger tumor size, lymph node metastasis, and extra-thyroidal extension and other studies also found a statistically significant relation between YAP1 expression and extra-thyroidal extension." (PMID 37383164, 2023). "Lymph node metastasis and high YAP1 expression showed significant association with the ODX low-risk group of RS < 26 (lymph node metastasis: OR 0.189, 95%CI 0.067–0.536, p = 0.002; high YAP1: OR 0.302, 95% CI 0.172–0.528, p < 0.001)." (PMID 37894401, 2023). "Overexpression of TRG-AS1 is associated with advanced TNM stage, lymph node metastasis, and shorter overall survival, which promotes cell proliferation, invasion, and migration of TSCC (tongue squamous cell carcinoma) by mediating the miR543/YAP1 axis." (PMID 34136488, 2021).
lymph node metastasis (continued). "Moreover, the expression of nuclear YAP1 was positively correlated with clinical stage, tumor size, and lymph node metastasis, while HSPC111 expression was significantly correlated with lymph node metastasis." (PMID 29113304, 2017). "Additionally, we found that YAP1 expression correlated with lymph node metastasis, clinical stage, and tumor size, while HSPC111 expression correlated with lymph node metastasis alone." (PMID 29113304, 2017). "Notably, nuclear expression of YAP1 was positively correlated with clinical stage (P = 0.041), tumor size (P = 0.023), and lymph node metastasis (P = 0.007), while HSPC111 expression was correlated with lymph node metastasis (P = 0.014)." (PMID 29113304, 2017). "Moreover, high-expression of YAP1 was associated with Borrman's types, WHO's histological types, lymph node metastasis, distant metastasis, and TNM staging." (PMID 27835600, 2016). "Meanwhile, patients with high expression of PP1γ, YAP1, and SOX2, tumor invasion depth, lymph node metastasis, advanced AJCC stage, and nerve invasion had significantly shorter PFS (P < 0.05)." (PMID 40626009, 2025). "The expression levels of nuclear YAP1 and HSPC111 were both significantly related to lymph node metastasis (P = 0.007 and P = 0.014, respectively)." (PMID 29113304, 2017). "Activation of YAP1 or inactivation of LATS1 enhances the proliferation and invasiveness of CC cells, correlating with unfavorable prognostic factors such as low histological grade, early recurrence, and lymph node metastasis." (PMID 41256331, 2025). "Additionally, survival analysis showed that patients with high expression of YAP1 and SOX2, male gender, lymph node metastasis, and advanced AJCC stage had significantly shorter OS (P < 0.05)." (PMID 40626009, 2025). "Multivariate linear regression analysis revealed menopause status (p = 0.047) and higher Ki67 LI (p < 0.001) as positively correlated factors with ODX RS, whereas lymph node metastasis (p = 0.003) and YAP1 expression (p = 0.002) showed a significant negative correlation with ODX RS." (PMID 37894401, 2023). "Moreover, YAP1 mRNA levels were significantly decreased in PCa patients irrespective of lymph node metastasis (N0, p = 7.45 × 10−10; n = 345 and N1, p = −1.36 × 10−9; n = 79) as compared to normal controls (n = 52)." (PMID 31835563, 2019). "In addition, survival analysis with regard to YAP 1 expression and a subset of pT2-4 UCB patients without lymph node metastasis (pT2-4/pN-, n = 64) showed that expression of YAP1 was also a significant prognostic factor (P = 0.004)." (PMID 23870412, 2013).
medulloblastoma (22 papers, 2013 to 2025). A malignant, invasive embryonal neoplasm arising from the cerebellum. "In contrast, Yap regulates neuronal differentiation via Shh signaling, and Yap1 is amplified in Hh-associated medulloblastomas and mediates Shh-driven neural precursor proliferation." (PMID 36720733, 2023). "WNT-positive medulloblastomas were strongly linked to nuclear and cytoplasmatic immunoreactivity for b-catenin, filamin A, and YAP1, whereas SHH-activated tumors showed immunoreactivity for GAB1, YAP1, and filamin A." (PMID 33497354, 2021). "Yap1 protein is amplified and upregulated in hedgehog‐associated medulloblastomas, while the quantified YAP1 pS127 site indicates inactivation of the protein in this subtype." (PMID 34569154, 2021). "Furthermore, IRS1 regulates the nuclear localization of YAP1, which causes the proliferation of cerebellar neural precursors in hedgehog-associated medulloblastomas." (PMID 36768755, 2023). "The amplification of YAP1 has been detected in different cancers including medulloblastoma, metastatic brain cancer and oesophageal squamous cell carcinoma." (PMID 33803512, 2021). "In medulloblastoma, YAP1 is significantly amplified and upregulated in SHH-activated subtypes and mediates SHH-driven NPC proliferation." (PMID 34012965, 2021). "Our finding of YAP1 directed HELLS upregulation in SHH medulloblastoma suggests a role for HELLS regulated chromatin remodeling in SHH medulloblastoma." (PMID 31541170, 2019). "In this study, we investigated the possibilities of using the intracellular protein markers GAB1, β-catenin, filamin A, and YAP1 for the determination of defined molecular subgroups of medulloblastoma under in vitro conditions." (PMID 28231263, 2017). "WNT medulloblastomas show nuclear accumulation of β-catenin protein in addition to Yap1 immunoreactivity in tumor nuclei and express Otx2." (PMID 27781424, 2016). "SHH-activated medulloblastomas express specific target proteins such as p75NGFR and Gab1, share expression of nuclear Yap1 with the WNT medulloblastoma, but lack Otx2 expression." (PMID 27781424, 2016). "The WNT pathway medulloblastomas (n = 4) were identified by a combination of positive YAP1 staining, as well as nuclear and cytoplasmic immunoreactivity to β-catenin." (PMID 24252460, 2013). "In addition, expression analysis on the GSE85217 dataset (693 patient cohort) showed that YAP1 is overexpressed specifically in the aggressive subtype alpha, compared to other subgroups and subtypes of medulloblastoma." (PMID 34944872, 2021). "Herein, we have assessed transcriptomic public records of two microarray datasets and found that YAP1 is explicitly overexpressed in patients profiled as poor responders to SMO inhibitors (e.g., Sonidegib, Vismodegib) and in SHH medulloblastoma subtype alpha." (PMID 34944872, 2021). "These experiments indicate YAP1/TEAD binding to HELLS upstream DNA, suggesting direct regulation of HELLS transcription by YAP1/TEAD in SHH medulloblastoma." (PMID 31541170, 2019). "Here we have identified YAP1 mediated, Sonic hedgehog induced upregulation of HELLS in murine models of cerebellar development and SHH medulloblastoma." (PMID 31541170, 2019). "In primary medulloblastoma tissues, these groups are thought to be distinguishable using the immunohistochemical detection of β-catenin, filamin A, GAB1 and YAP1 protein markers." (PMID 28231263, 2017). "All four of these tumors positive for nuclear β-catenin also displayed YAP1 immunoreactivity, and have therefore been classified as a WNT subtype medulloblastoma." (PMID 24252460, 2013).
medulloblastoma (continued). "More recently, studies have shown that YAP1 expression leads to upregulation of chromatin remodeler helicase, lymphoid specific (HELLS) in SHH-activated medulloblastoma and is activated downstream of SHH pathway activation through SMO, a positive transducer of SHH signaling." (PMID 34012965, 2021). "In addition, the YAP1 protein is highly detected in the SHH subtype and shows a slight preference for medulloblastoma with extensive nodularity (MBEN) histological subtype (through immunohistochemistry)." (PMID 34944872, 2021). "These novel findings add to our understanding of the downstream activity of the SHH pathway and may help bridge the gap between the downstream effector YAP1 and the unregulated proliferation in SHH medulloblastoma." (PMID 31541170, 2019). "However, knockdown of YAP1 in murine medulloblastoma slice culture also resulted in decreased levels of HELLS mRNA and protein, indicating that HELLS is regulated through YAP1." (PMID 31541170, 2019). "Indeed, the verteporfin induced decrease in CyclinD1 or D2 in CGNPs and MBCs links the YAP1/HELLS axis to a requirement for proliferation in the developing cerebellum and SHH medulloblastoma tumor cells." (PMID 31541170, 2019). "YAP1 amplification, even though identified as characteristic for various subgroups of medulloblastoma was not assessed in this study." (PMID 29869738, 2018). "Non-WNT/non-SHH medulloblastomas finally express Otx2 but lack the other markers such as Yap1 (which is only expressed in endothelial cells in this tumor type serving as internal control and nuclear β-catenin." (PMID 27781424, 2016). "A lack of YAP1 immunoreactivity in medulloblastoma tumors is indicative of the Non-WNT/SHH subgroup (encompassing both Groups 3 and 4)." (PMID 24252460, 2013).
pulmonary fibrosis (22 papers, 2018 to 2026). Chronic progressive interstitial lung disorder characterized by the replacement of the lung tissue by connective tissue, leading to progressive dyspnea, respiratory failure, or right heart failure. "According to a different study, calycosin’s ability to mitigate pulmonary fibrosis was achieved via controlling the miR-375/Yes-associated protein 1(YAP1) signaling pathway, which prevented TGF-β1-induced epithelial–mesenchymal transition (EMT)." (PMID 38666911, 2024). "In addition, miR-15a has been shown to inhibit lung fibrosis by targeting the yes-associated protein 1 (YAP1), a key downstream effector of the Hippo pathway." (PMID 33807742, 2021). "We further found that after BLM challenge, YAP1-cKI mice exhibited an improved pulmonary respiratory capacity and attenuation of pulmonary fibrosis." (PMID 38945958, 2024). "We then established transgenic mice with conditional YAP1 knockout in AT2 cells by crossing YAP1fl/fl mice with Sftpc-labeled Cre (Sftpc-Cre) mice to explore the role of YAP1 in pulmonary fibrosis." (PMID 38945958, 2024). "The findings showed that increasing YAP1 levels in alveolar type II cells reduced lung fibrosis by improving the function of mitochondria and decreasing cell aging." (PMID 38945958, 2024). "The effect of YAP1 on AT2 cells during pulmonary fibrosis depended on the modulation of cellular senescence and mitochondrial function mediated through targeting of Prdx3." (PMID 38945958, 2024). "In this study, we first revealed that increased expression of YAP1 in AT2 cells mitigated BLM-induced pulmonary fibrosis and revealed the regulatory relationship between YAP1/TEAD1 and Prdx3." (PMID 38945958, 2024). "Taken together, these findings demonstrated that overexpression of YAP1 in AT2 cells inhibited BLM-induced pulmonary fibrosis." (PMID 38945958, 2024). "Overexpression of Prdx3 suppressed experimental pulmonary fibrosis, whereas silencing Prdx3 partially abrogated the protective effect of YAP1." (PMID 38945958, 2024). "Our study demonstrated that cytoplasmic circELP2‐mediated mitochondrial quality control pathway accelerated pulmonary fibrosis via targeting YAP1/TAZ by sponging miR‐630." (PMID 38159063, 2024). "Our study showed that mice deficient in YAP1 in AT2 cells exhibited deterioration of lung respiratory function and exacerbation of pulmonary fibrosis following BLM administration." (PMID 38945958, 2024). "Overexpression of YAP1 prevented lung senescence, restored lung structure, and inhibited pulmonary fibrosis." (PMID 38945958, 2024). "Micro-CT analysis also showed that YAP1 knockdown in AT2 cells exacerbated pulmonary fibrosis after BLM induction." (PMID 38945958, 2024). "Obvious increases in collagen deposition and the degree of pulmonary fibrosis after BLM challenge were detected in YAP1-cKO mice compared to WT mice by Masson’s trichrome staining, immunohistochemical analysis, and hydroxyproline content measurement." (PMID 38945958, 2024). "Regarding the effect of YAP1 on pulmonary fibrosis, research has shown that the inhibition of YAP/TAZ through dopamine receptor D1 in lung fibroblasts reduces pulmonary fibrosis." (PMID 38945958, 2024). "We established a mouse model of pulmonary fibrosis by intratracheal BLM administration to further explore the function of YAP1." (PMID 38945958, 2024). "Yes-associated protein 1 (YAP1) is essential for cell growth and organ development; however, the role of YAP1 in AT2 cells during pulmonary fibrosis is still unclear." (PMID 38945958, 2024). "Here, by using murine lineage tracing coupled with injury-repair models and spatial transcriptomics studies, we uncovered a method to treat lung fibrosis by promoting AT1 cell differentiation through inhibition of Yap1." (PMID 37166104, 2023). "Vice versa, inactivation of both Yap1 and Wwtr1 (encoding Taz) or Wwtr1 alone in AT2 cell stem cells impaired alveolar epithelial regeneration and resulted in increased pulmonary fibrosis upon bleomycin injury." (PMID 37166104, 2023).